KRT19 (keratin 19)
Diseases named in the same sentence as KRT19 in open-access papers (continued):
Sharing a sentence is not in itself a finding about the gene and the disease.
cancer (395 papers, 2003 to 2026). A tumor composed of atypical neoplastic, often pleomorphic cells that invade other tissues. "A comprehensive RNA-Seq analysis revealed significant mRNA upregulation of several genes, including ACTA1, IGFBP2, MUC5B, CEACAM5, and KRT19, all of which are associated with cancer progression in various types of malignancies (p < 10−10)." (PMID 40004774, 2025). "Two of these (cancer cells and LEC1, cancer cells and LEC2) exhibited high expression of cancer cell-associated genes such as KRT19, CDH1, MUC1, and TFF1, suggesting their close interaction with cancer cells." (PMID 41249124, 2025). "HuH-7 cells also express large quantities of keratin 19 (K19), a type I intermediate filament that is strongly implicated in the progression of various human carcinomas." (PMID 41306287, 2025). "KRT19, a constituent of the keratin family, plays a significant role in numerous processes associated with cancer." (PMID 39507894, 2024). "We focused on KRT13 as a candidate gene responsible for radioresistance in pancreatic CSC because an association of some KRT family genes, such as KRT19, with the stemness of normal and cancer cells has been reported." (PMID 36610719, 2023). "Third, when a preformed, noncovalent complex of KRT19 and CXCL12 was incubated with TGM2 at 20 °C, a covalent CXCL12–KRT19 heterodimer was generated that resembled that which is associated with cancer cells." (PMID 35046049, 2022). "PCA loadings show that the genes exerting the largest effects include MMP1 and MMP10, KRT7, and KRT19, high levels of which in other cancers have been associated with unfavorable prognosis." (PMID 35480116, 2022). "Liquid bead array hybridization assay has been applied as a predictive and prognostic index of cancer patients and guiding clinical treatment, making KRT19 based CTC a promising diagnostic method for SCC." (PMID 33442422, 2021). "These contrary results persuaded us to examine the mechanism underlying the association between KRT19 and cancer progression." (PMID 30650643, 2019). "Immunohistochemistry (IHC) and immunofluorescence staining for CD133 as well as other cancer-associated proteins, including cytokeratin 19, TGF-β1, p-Smad2 and epithelial–mesenchymal transition (EMT) markers S100A4, E-Cadherin and Vimentin were analyzed." (PMID 29510695, 2018). "As the fold change threshold increased (>3.0), the number of differentially expressed genes decreased, but core regulatory genes such as ADGRL2, NR2F1, S100A16, and KRT19 remained consistently altered, highlighting isoform-specific regulation of key cancer-associated genes." (PMID 41300774, 2025). "The remarkably specific association of CXCL12 with KRT19 on cancer cells in human and mouse tumors and on human cancer cell lines may be a consequence of the manner in which the CXCL12–KRT19 coating is formed." (PMID 35046049, 2022). "Combined staining of AChE and the PCa cell marker Cytokeratin 19 (CK19) using double-immunofluorescence (IF) staining confirmed strong co-localization of CK19 with AChE, underlining the specificity of AChE expression in cancer cells." (PMID 33357230, 2020). "However, the differential role of KRT19 regarding molecular cancer progression and the mechanisms underlying these differences remain elusive." (PMID 30650643, 2019). "KRT19 is also a differential regulatory factor implicated in cancer progression." (PMID 30650643, 2019). "Thus, the molecular mechanism underlying the contradictory roles of KRT19 in various cancers needs to be examined to reveal the function of KRT19 in specific cancers." (PMID 30650643, 2019). "We next aimed to explore the underlying mechanism by which KRT19 regulates cancer reprogramming." (PMID 29747452, 2018). "Cytokeratin 19 (CK19), a 40 kDa acidic cytokeratin (Type I), is normally expressed in stratified squamous epithelium and it has been considered a marker of pre-malignancy and susceptibility to cancers like the OSCC." (PMID 26672675, 2015).
cancer (continued). "Hence, the diagnostic value of cytokeratin 19 in parathyroid pathology is low but this antigen could rather evoke scientific interest because of its up-regulation in carcinoma." (PMID 35805976, 2022). "In our study, this silent mutation in KRT19 may also play a critical role in diverse cancers, but further detailed study might be needed to explore the possible potential role of silent mutation in KRT19 in diverse cancers." (PMID 30650643, 2019). "KRT19 and ERα play a promoting role in a variety of cancers, but there are few reports on the relationship between the two effects." (PMID 39453570, 2025). "These genes, including immunoglobulin-related genes, Transgelin (TAGLN), Keratin 19 (KRT19), Metastasis-associated lung adenocarcinoma transcript 1 (MALAT1), and superoxide dismutase (SOD2), play a role in the EMT process in various cancers." (PMID 41035074, 2025). "Cancer cells in LysM-Tert-KO mice also tended to have a reduced expression of the epithelial marker cytokeratin 19 (CK19) suggesting their dedifferentiation." (PMID 40482194, 2025). "Accumulating evidence has shown that KRT19 is abnormally expressed and correlates to poor prognosis in various cancers." (PMID 41345704, 2025). "We also found by Ualcan analysis of the TCGA database that the expression of ESR1 and KRT19 in different cancer stages, races, genders, age groups, histological subtypes, and lymph node metastasis status were significantly different in THCA (All P < 0.05)." (PMID 39453570, 2025). "The integrative analysis identified PROX1+ LEC subsets, JAM2+ BECs, COL1A1+ stromal cells, PTPRC+ leukocytes, including MZB1+ plasmablasts, KRT19+ cancer cells, and MKI67+-proliferating cells." (PMID 41249124, 2025). "Through correlation analysis, we observed that LAD1 expression levels were statistically associated with several cancer-related genes, including SFTPB, S100A6, CEACAM6, KRT19, S100A10, ANXA2, S100A11, and CAPN2." (PMID 41423496, 2025). "No oncofetal genes were significantly upregulated in PGCC's early progeny, whereas 19 genes were suppressed (including HLF and KRT19), compared with initial cancer cells." (PMID 41287033, 2025). "Unbiased clustering using UMAP identified several cell types, including KRT19+ cancer cells, CD3E+ T cells, MS4A1+ B cells, MZB1+ plasmablasts, FLT3+ dendritic cells (DCs), and PROX1+ LECs, which were then visualized within the tissue context." (PMID 41249124, 2025). "4.CYFRA 21–1, a fragment of cytokeratin 19, has been studied as a biomarker for various cancers, including OSCC." (PMID 40027232, 2025). "As CCL11 is a secreted protein, we confirmed these finding as well as the cancer cell origin of this chemokine by staining for Ccl11 and Krt19 using RNA fluorescence in situ hybridization." (PMID 38195933, 2024). "KRT19 was reported as a potential immunotherapy target, and overexpression of this molecule promotes the proliferation and migration of cancer cells via Wnt/β-catenin signaling." (PMID 38510654, 2024). "To confirm the development of fibrotic tissue within the PanINs, we next performed immunofluorescent staining for the fibroblast activation protein α-smooth muscle actin (αSMA) and the cancer cell marker Keratin-19 (KRT19)." (PMID 38654064, 2024). "MALAT1 and SOD2 were universally expressed across all these cell types while KRT19 demonstrated higher expression in cancer and Ascending Thin Limb of Loop of Henle cells (LoH ATL cells)." (PMID 38431724, 2024). "Among these cell type markers of cell clusters, cancer cell cluster specifically expressed keratin 19 (KRT19) and CEA cell adhesion molecule 1 (CEACAM1), and TAM cluster expressed CD68, CD163, and complement C1q C chain (C1QC)." (PMID 38302412, 2024). "In stroma-enriched 3D model, Cytokeratin 19 and E-cadherin were expressed only by cancer cells while vimentin and fibronectin were expressed by fibroblasts." (PMID 38951897, 2024).
cancer (continued). "This includes functionally relevant proteins associated with LN metastasis in cancer such as KRT7, KRT19, SRI, NPM1, Annexin A2 (ANXA2), Annexin A5 (ANXA5)." (PMID 37142981, 2023). "We present several case studies with varying stages of cancer development (I−III), mutation status (EGFR, ALK), and biomarker expression based on a three-gene panel (CD133, KRT19, and MUC1)." (PMID 36900350, 2023). "We used the canonical markers cytokeratin 17 (CK17) for the basal subtype, GATA6 for the classical subtype, and cytokeratin 19 (CK19) as a pan-cancer cell marker." (PMID 36781852, 2023). "P0825 expressed high levels of cancer markers KRT19 and EpCam, cancer stem marker Sox9, Hippo oncogenic co-activator Yap1, and EMT marker Vimentin." (PMID 36865791, 2023). "It has been demonstrated that the evolutionarily old KRT19 is differentially expressed in several types of cancers." (PMID 36949761, 2023). "We performed multiplex immunostaining using cytokeratin-19 (CK-19; as a marker of cancer cells) and pMLC2 (as a marker of amoeboid cells and Myosin II activity)." (PMID 37851808, 2023). "To date, KRT19 remains the only keratin that has been reported to be one of the cancer stemness markers including CD133, EpCAM and c-kit in HCC." (PMID 35706019, 2022). "Cytokeratin 19 is a marker for cells of epithelial origin and was used to differentiate between the inoculated cancer cells and other parts of the graft, such as CAM, blood vessels, or immune infiltrates." (PMID 36428644, 2022). "Firstly, the difference between KRT19 expression in different cancer types and normal tissues was observed using the TCGA and GTEx database." (PMID 36292723, 2022). "Immunofluorescence images showed cytokeratin 19 (CK19)-positive cancer glands intermixed with vimentin-positive CAFs in the CIPCO." (PMID 35565206, 2022). "These experiments predicted that preventing expression by cancer cells of either KRT19 or TGM2 would impair formation of the CXCL12–KRT19 coating and allow T cells to accumulate within cancer cell nests." (PMID 35046049, 2022). "Experiments with mice have revealed that Krt19+/Lgr5−cells are radioresistant cancer-initiating stem cells in the colon and intestine, which can partially explain the poorer prognosis of tumors with higher KRT19 expression." (PMID 35428170, 2022). "KRT19 is a known prognostic biomarker for multiple cancer types, including PCs, and increased KRT19 was closely correlated with a poor prognosis of patients with PC." (PMID 35428170, 2022). "We chose these peptides because these genes, such as Annexin 2, Calprotectin A8, Calprotectin A9, Keratin 19, Keratin 8, Angiopoietin-1, Tissue inhibitor of metalloproteinase (TIMP), and Afamin, are associated with cancer progression." (PMID 36672532, 2022). "Recently, altered expression of several keratins including keratin 6 (KRT6), KRT14, KRT15, KRT16, KRT17 and KRT19 were reported to coordinate tumorigenesis in different types of cancers." (PMID 35706019, 2022). "That CXCL12 is cross-linked to KRT19 allows the heterodimer to self-assemble with KRT8, which is also secreted, into a higher-order filamentous network that coats the cancer cell." (PMID 35046049, 2022). "Based on the close relationship between the expression of KRT19 and immune infiltration, we made further exploration about cancer-immunity cycle." (PMID 36292723, 2022). "Recently, a statistically significant up-regulation of cytokeratin 19 was found in proliferating parathyroid lesions encompassing adenoma, multiglandular parathyroid disease and carcinoma." (PMID 35805976, 2022).
cancer (continued). "As a cytoplasmic intermediate filament protein, KRT19 can regulate diverse properties in various cancers through interacting with a variety of signal transduction molecules." (PMID 33767587, 2021). "Collectively, these data further demonstrated that the cancer promoting function of Linc-KILH was dependent on the presence of KRT19 in HCC cells." (PMID 33767587, 2021). "In vitro and in vivo functional experiments in Huh7, MHCC-97H and Hep3B cells revealed that the cancer promoting function of Linc-KILH on HCC cells was dependent on KRT19 expression." (PMID 33767587, 2021). "The expression of KRT19 in cancer cells increases their cell proliferation rate due to its ability to stabilize cyclin D3." (PMID 34575702, 2021). "KRT7, KRT18, KRT19 protein expression in tumors were reported to predict prognosis in several cancer types." (PMID 34070214, 2021). "We identified 559 cancer cells according to epithelial and cancer markers including KRT19, KRT7, EPCAM, SOX9, and KRT23." (PMID 34326696, 2021). "CYFRA 21-1 is a measurement of cytokeratin 19 (CK19) fragment, also known as a pan-carcinoma marker." (PMID 34957244, 2021). "Although focal galectin-3, HBME-1, and cytokeratin-19 expression were encountered in benign FPTLs, diffuse positive reactions for these three markers were more characteristic of carcinomas." (PMID 34711014, 2021). "CYFRA 21-1 is a fragment of cytokeratin-19 (an epithelial cell filament) produced during cancer cell differentiation." (PMID 32685054, 2020). "Both KRT8 and KRT19 have been well demonstrated to function as two oncogenes in development of human cancers." (PMID 32519739, 2020). "This miR was identified to be located within the HB marker gene keratin 19 (KRT19), a marker for hepatic progenitors and cancer stem cells, previously related to the metastatic progression of HCC." (PMID 30909459, 2019). "In light of previous studies, we aimed to knock down KRT19 expression in both (breast and colorectal) cancer cell lines using lentiviral-mediated shRNA and the RRE/REV lentivirus expressing system." (PMID 30650643, 2019). "Compared to our previous findings, we found the opposite effect regarding the β-catenin/RAC1 complex; the fraction, ICC, Co-IP, and ChIP assay results confirmed that the role of KRT19 in different cancers is governed by differential mechanisms." (PMID 30650643, 2019). "The current study revealed that the differential role of KRT19 in different cancers is due to interactions with either β-catenin alone or with the β-catenin/RAC1 complex, and consequent stabilization and nuclear import of the molecular complex." (PMID 30650643, 2019). "In our previous study, we found that KRT19 was obligatory for cancer and cancer stem cell progression because of its selective regulation of the NUMB-dependent Notch signaling pathway." (PMID 30650643, 2019). "Immunofluorescence colony staining for CRCs showed that the cytoplasm of cancer cells was clearly stained with anti‐cytokeratin 19 monoclonal antibody." (PMID 31044541, 2019). "Concurrently, in our previous study, we showed a consistent role for KRT19 in enhancing cancer properties." (PMID 30650643, 2019). "KRT19 regulated cancer stem cell reprogramming by modulating the expression of cancer stem cell markers (ALDH1, CXCR4, and CD133), as well as the phosphorylation of Src and GSK3β (Tyr216)." (PMID 29747452, 2018). "We found that the knockdown or overexpression of KRT19 in MDA-MB231 or KU-CSLCs cells modulated cancer reprogramming and drug sensitivity, as compared to normal MDA-MB231 or KU-CSLCs." (PMID 29747452, 2018). "This implies that through OCT4, KLF4, NANOG, and SOX2 alteration, KRT19 regulates cancer stem cell reprogramming efficiency in KU-CSLCs." (PMID 29747452, 2018). "In our data, KRT19 not only regulates cancer stemness, metastasis, and drug resistance, but it also modulates the expression of stemness, metastatic, and drug-resistant markers." (PMID 29747452, 2018).
cancer (continued). "In this study, we further demonstrated that the knockdown of KRT19 in MDA-MB231 cells significantly induced cell proliferation and sphere formation, suggesting that KRT19 is a potent cancer suppressor gene." (PMID 29747452, 2018). "The sensitivity of the RT-LAMP for KRT19 in OSCC patients was lower than has been reported in other cancers." (PMID 26700817, 2016). "Cancer initiation occurs as a result of specific migration, expansion and transformation of cytokeratin-19+-liver (CK-19+) cells." (PMID 27323406, 2016). "KRT15 and KRT19 are also downregulated in OSCC, and the expression levels of the remaining KRT15 and KRT19 represent differentiation and the invasive potential of the cancer, respectively." (PMID 27512993, 2016). "Previous studies have indicated that KRT19 contributed toward the maintenance of cancer stem cells (CSCs)." (PMID 27833076, 2016). "As KRT19 binds to HER2 intracellularly and leads to the subsequent phosphorylation of HER2 and Erk, targeting KRT19 is a potential therapeutic option for HER2-driven cancers." (PMID 28008968, 2016). "Based on the regulation pattern of miRNAs in human carcinoma reported, we detected the mRNA and protein expression of KRT19 in the two cell lines treating with miR-26a mimics or inhibitor." (PMID 27833076, 2016). "Cytokeratin 19 and vimentin expression was analysed in the carcinomas in order to evaluate if injected cancer cells can give rise to distinct cell types." (PMID 25885700, 2015). "We detected variations in quantity of cathepsin D, cathepsin B, squamous cell carcinoma antigen, γ synuclein, cytokeratin 19 and other proteins that have been reported to play a role in cancer etiology." (PMID 18416831, 2008). "VM structures formed by cancer cells exhibited a lower vascular integrity, as shown by a decreased cytokeratin 19+/VE-cadherin+ area, while vessels formed by endothelial cells showed a significantly higher vascular integrity, as represented by an increased VE-cadherin+/CD31+ area." (PMID 41294859, 2025). "PROM1 (Cluster 4) links KRT19 suppression to cancer stem cell (CSC) dynamics." (PMID 40806403, 2025). "Moreover, we observed an increased expression of COL1A2 and KRT19 in cancer patients with an advanced stage of the disease." (PMID 39273514, 2024). "Furthermore, the IF analysis of CRC tissues revealed that a significant FSTL3 expression was shown by KRT19-positive cancer cells." (PMID 38302412, 2024). "In a previous study, our group concluded that the detection of COL1A2 and KRT19 mRNA in the extracellular vesicles (EVs) of patients with advanced malignant solid tumors could be a valid and reliable neoplastic detection method." (PMID 39273514, 2024). "This could enable the measurement of expressions of certain molecular markers, such as the epithelial marker cytokeratin 19, mesenchymal marker plastin 3, and cancer stem markers ALDH1, CD133, and CD44." (PMID 36835361, 2023). "Based on the significant fold change in LN positive GBC in mass spectrometric data and literature survey for their functional relevance and association with LN metastasis in cancer, we selected four proteins namely KRT7, KRT19, SRI and NPM1 for verification using Western blot analysis." (PMID 37142981, 2023). "EpCam and KRT19 were reported as prognostic cancer markers correlated with clinical outcome." (PMID 36865791, 2023). "The protein level of KRT19 in cancers was also explored from the CPTAC dataset." (PMID 36292723, 2022). "The KRT19+ cancer cells were specifically stained with anti-CXCL12 antibody." (PMID 35046049, 2022). "Notably, KRT19 has been recently described to protect cancer cells from the immune system, acting in concert with transglutaminase 2 (TGM2) which was also found to be elevated at the mRNA level in Ptenflox/flox prostates of 20-week-old mice." (PMID 36291720, 2022).